DLX6 (distal-less homeobox 6)
Tractability: No criterion of Open Targets' tractability assessment is met for any kind of drug.
Gene: Protein-coding gene on chromosome 7 (97,005,553 to 97,011,040, forward strand). Ensembl gene ENSG00000006377.
Subcellular location: Nucleus
Subcellular location (Human Protein Atlas): Nuclear bodies
Pathways (Reactome):
Gene expression (Transcription): Regulation of RUNX2 expression and activity
Gene Ontology:
Molecular function: sequence-specific double-stranded DNA binding; DNA-binding transcription factor activity; DNA-binding transcription factor activity, RNA polymerase II-specific; RNA polymerase II cis-regulatory region sequence-specific DNA binding; DNA binding
Biological process: cell differentiation; embryonic skeletal system development; nervous system development; regulation of transcription by RNA polymerase II; skeletal system development; regulation of DNA-templated transcription
Cellular component: chromatin; nucleus
Genetic constraint (gnomAD): Loss-of-function variants: 4 observed, 24.13 expected, observed/expected ratio (o/e) 0.17, 90% interval 0.081 to 0.38. The synonymous counts are far from expectation, so gnomAD's model fits this gene poorly and the ratio says little. Missense variants: 382 observed, 348.27 expected, observed/expected ratio (o/e) 1.1, 90% interval 1.01 to 1.19. Synonymous variants: 184 observed, 145.67 expected, observed/expected ratio (o/e) 1.26, 90% interval 1.12 to 1.43.
Homologues: Orthologues: chimpanzee DLX6 (100% identical), macaque DLX6 (99% identical), pig DLX6 (98% identical), rat Dlx6 (98% identical), dog DLX6 (97% identical), mouse Dlx6 (97% identical), guinea pig DLX6 (81% identical), tropical clawed frog dlx6 (75% identical), zebrafish dlx6a (71% identical), rabbit DLX6 (51% identical). Paralogues in human: DLX1 (52% identical), DLX4 (37% identical), DLX2 (34% identical), DLX5 (34% identical), DLX3 (32% identical), NANOG (19% identical), NANOGP8 (19% identical), BSX (16% identical), VENTX (11% identical).
Diseases named in the same sentence as DLX6 in open-access papers:
DLX6 is named in the same sentence as 38 diseases in open-access papers, as found by Europe PMC text mining. Sharing a sentence is not in itself a finding about the gene and the disease. The quoted sentences say what the papers report.
breast carcinoma (5 papers, 2010 to 2022). "To analyze the role of DLX2, DLX5, and DLX6 in breast primary tumor and metastasis formation, we used an experimental model of breast cancer metastasis." (PMID 21108812, 2010). "Thus, the biological significance of DLX6 and CNGB1 gene mutations in lung adenocarcinoma patients with breast cancer still needs to be further investigated." (PMID 35668376, 2022). "Morini found that DLX6 involves in the metastasis potential of breast cancer." (PMID 31874629, 2019). "Furthermore, the mutations of TRIM73, DLX6 and CNGB1 and high expression of FGF10 and VEGFA might play an important role in the development of lung adenocarcinoma in breast cancer patients." (PMID 35668376, 2022). "Dlx-2 has been shown to be expressed at higher levels in human breast cancers compared to other Dlx genes, including Dlx-1, Dlx-3, Dlx-4, and Dlx-6, although its precise roles in tumor biology are not clear." (PMID 21917150, 2011). "Thus, TRIM73, DLX6 and CNGB1 may be relatively characteristic genes in pulmonary adenocarcinoma patients with previous breast cancer." (PMID 35668376, 2022). "In mammary tumors, the expression levels of DLX1, DLX3, DLX4 and DLX6 did not significantly differ from those observed in normal tissue (data not shown)." (PMID 21108812, 2010).
cleft palate (4 papers, 2014 to 2025). Cleft palate is a fissure type embryopathy that affects the soft and hard palate to varying degrees. "Sequencing of DLX5 and DLX6 in a cohort of humans with isolated cleft palate has shown causal effects of missense mutations in DLX5." (PMID 28053980, 2016). "Research on a canine model of Pierre Robin Sequence revealed that a LINE-1 insertion in the homologue to the human DLX6 gene is responsible for cleft palate and associated mandibular abnormalities." (PMID 28053980, 2016). "Mutations in the DLX6 and ADAMTS20 genes are associated with the development of cleft palate and other abnormalities in dogs." (PMID 40431567, 2025). "A genome-wide association study of Nova Scotia Duck Tolling Retrievers with naturally occurring cleft palate led to the investigation of two homeobox genes, DLX5 and DLX6." (PMID 24699068, 2014).
autism (2 papers, 2005 to 2011). Persistent deficits in social interaction and communication and interaction as well as a markedly restricted repertoire of activity and interest as well as repetitive patterns of behavior. "Chromosome 7q, also an important region in linkage studies of autism, contains DLX5 and DLX6." (PMID 16266434, 2005).
hearing loss (2 papers, 2010 to 2021). "In one report, a human breakpoint located at 38 kb telomeric to DSS1 and at 258 kb centromeric to DLX6 is associated with SHFM and hearing loss phenotype." (PMID 20808887, 2010).
mandibular deficiency (2 papers, 2014 to 2021). "The present study was carried out to determine the role of DLX6 gene variations in mandibular deficiency." (PMID 33815981, 2021). "Hence this study centralized on evaluating DLX6 gene variations contributing to mandibular deficiency." (PMID 33815981, 2021). "Hearing loss and craniofacial defects including cleft palate and micrognathia have been observed in the deletion of a DLX5 and DLX6 enhancer region." (PMID 24699068, 2014). "It showed no SNPs in any of the exons of the DLX6 gene of all 30 samples indicating non-involvement of DLX6 gene in mandibular deficiency." (PMID 33815981, 2021).
Cognitive impairment (1 paper, 2024). Abnormal cognition is characterized by deficits in thinking, reasoning, or remembering. "The significance of the associations between cognitive impairment and increased expression levels of DLX6 and PRB2 was marginally below the threshold (z-score = 3.582; p-value = 3.41 × 10−4PRB2; z-score = 3.699; p-value = 2.17 × 10−4, respectively)." (PMID 38542318, 2024).
colorectal cancer (1 paper, 2025). A primary or metastatic malignant neoplasm that affects the colon or rectum. "Elevated DLX6 expression has been implicated in several cancers, including hepatocellular carcinoma and colorectal cancer, where it promotes proliferation, invasion, and metastasis." (PMID 40098953, 2025).
developmental delay (1 paper, 2021). "Human study done shows DLX6 gene affected members to be having features other than mandibular retrognathia like hearing loss, abnormal pinnae, ectrodactyly, cleft palate, developmental delay and abnormal teeth." (PMID 33815981, 2021). "A study on humans has shown multiple individuals with deletion of DLX5 and DLX6 who had reported severe phenotypes including ectrodactyly, hearing loss, abnormal pinnae, cleft palate, lower jaw retrognathia, developmental delay and abnormal teeth." (PMID 33815981, 2021).
endometriosis (1 paper, 2022). The growth of functional endometrial tissue in anatomic sites outside the uterine body. "AEBP1 and KLF2 were higher expressed, while DLX6, HOXB6, and RORB were lower expressed in endometriosis in the GSE7305 dataset." (PMID 36532015, 2022).
hepatocellular carcinoma (1 paper, 2025). A malignant tumor that arises from hepatocytes. "This study highlighted that DLX6 and its antisense RNA, DLX6-AS1, could serve as prognostic markers for hepatocellular carcinoma." (PMID 40098953, 2025).
Infertility (1 paper, 2022). "Simultaneous deletion of Dlx5 and Dlx6 in the postnatal uterus leads to alterations in uterine adenogenesis and infertility, suggesting that they act redundantly for epithelial morphogenesis in the uterus." (PMID 35909540, 2022).
liver cancer (1 paper, 2022). An epithelial or non-epithelial malignant neoplasm that arises from the liver. "In addition, the antisense of lncRNA distal-less homeobox 6 (DLX6-AS1), not only acts as a prognostic biomarker in liver cancer, but also the stemness of cancer cells in HCC patients." (PMID 35986343, 2022).
lung carcinoma (1 paper, 2015). "So far, the functions of DLX6 haven’t been reported in related researches, not to mention its expression level and working mechanisms in lung cancer." (PMID 26052251, 2015).
oral cancer (1 paper, 2024). "DLX6 promotes oral cancer cell proliferation and inhibits apoptosis, and the EGFR-CCND1 signaling pathway may be a potential mechanism involved in the regulatory axis." (PMID 38317839, 2024).
orofacial cleft (1 paper, 2014). A disorder of facial skeleton that is characterized by cleft lip and/or cleft palate that result in feeding, speech and hearing problems caused by failures during development. "Nine noncoding sequence variants were identified within DLX5 and DLX6 of human patients with orofacial clefts." (PMID 24699068, 2014).
schizophrenia (1 paper, 2024). A major psychotic disorder characterized by abnormalities in the perception or expression of reality. "The network, constructed based on the TFs predicted by genes with higher expression in ECM-altered regions in schizophrenia, is centered around HEY1 and DLX6, both of which are associated with neurogenesis and forebrain and craniofacial development." (PMID 38491019, 2024).
T-cell lymphoma (1 paper, 2021). "In murine T-cell lymphoma, aberrant expression of neighboring DLX5 and DLX6 was correlated with inversion of chromosome 6, juxtaposing the loci of these NKL homeobox genes with T-cell receptor gene Tcrb." (PMID 34829904, 2021). "DLX5 expression was also detected in primary human T-cell lymphoma samples while DLX6 tested negative." (PMID 34829904, 2021).
type 2 diabetic (1 paper, 2023). "We used db/db mice as a type 2 diabetic mice model and db/m mice as a non-diabetic control to observe the correlations between the lncRNA Dlx6-os1 expression level, urinary albumin protein level, and the degree of podocyte injury." (PMID 36854759, 2023).
tumor (5 papers, 2010 to 2025). "The findings indicated that high DLX6 expression was associated with a significant reduction in the immunity score, suggesting that DLX6 may play an inhibitory role in tumor immunity." (PMID 40098953, 2025). "Functional assays, CCK-8 experiments, and tumor formation experiments in BALB/c nude mice confirmed that DLX6 is a key gene in pathways enhancing intracellular autophagy, promoting tumor cell proliferation, and inhibiting tumor cell apoptosis." (PMID 40098953, 2025). "Immunohistochemistry and RNA sequencing were utilized to investigate the relationship between DLX6 expression in NPC tumor samples and clinical pathological factors." (PMID 40098953, 2025). "Considering the role of DLX6 in tumor immunity, we analyzed the potential impact of DLX6 in immunotherapy." (PMID 40098953, 2025). "Our findings demonstrate a strong correlation between DLX6 expression and immune-related chemokines and their receptors, highlighting DLX6’s critical role in tumor immunity and its potential as a target for immunotherapy." (PMID 40098953, 2025). "To investigate the relationship between DLX6 and tumor immunity, we initially examined the correlation between DLX6 expression and the Immunescore." (PMID 40098953, 2025). "High expression of DLX6 may promote tumor growth and metastasis by inhibiting the infiltration of various immune cells, thereby weakening tumor immune surveillance." (PMID 40098953, 2025). "Our study indicates that DLX6 is a novel prognostic biomarker and potential therapeutic target for NPC, playing a critical role in metastasis, angiogenesis, and tumor immunity." (PMID 40098953, 2025). "DLX6, a member of the distal-less homeobox (DLX) gene family, has garnered attention in cancer research due to its role in developmental processes and tumor progression." (PMID 40098953, 2025). "In this study, we identified the significant role of DLX6 in NPC, particularly its potential in cancer metastasis, angiogenesis, and tumor immune mechanisms." (PMID 40098953, 2025).
cancer (4 papers, 2017 to 2025). A tumor composed of atypical neoplastic, often pleomorphic cells that invade other tissues. "We further conducted an ssGSEA analysis of cancer hallmarks using sequencing and clinical data from patients at Fujian Cancer Hospital to elucidate the potential pathways and biological processes associated with DLX6." (PMID 40098953, 2025). "Few studies explore the association of DLX6 with cancers up to now." (PMID 35668376, 2022). "Our research scrutinized sequencing data and clinical records of patients at Fujian Cancer Hospital to explore the expression and function of DLX6 in NPC." (PMID 40098953, 2025). "Through GSEA KEGG enrichment analysis using sequencing and clinical data from patients at Fujian Cancer Hospital, we found that DLX6 was significantly enriched in t cell cycle, DNA replication, ECM receptor reaction and pathways in cancer." (PMID 40098953, 2025). "Bioinformatics analysis revealed that DLX6 is involved in pathways related to cell cycle, DNA replication, and cancer progression." (PMID 40098953, 2025). "As a conclusion, our robust network-based framework has derived 31 AS-related lncRNAs that not only validates known cancer-associated cases MALAT1 and HOXA11-AS, but also reveals new players such as DNM1P35 and DLX6-AS1with potential functional implications." (PMID 32760422, 2020).
Mendelian diseases (1 paper, 2018). "The six genes (SCARF2, RD3, COL9A3, FAM161A, RASGRP1 and DLX6) in common between novel contigs, human Mendelian diseases, and hereditary diseases in dogs are significant in known disease phenotypes in humans and animal models." (PMID 30022108, 2018).
DLX6 also shares sentences with these, for which no sentence is quoted: adenoid cystic carcinoma (1 paper); Brachycephaly (1); breast tumors (1); cleft lip (1); craniosynostosis (1); Ectodermal dysplasia (1); Ectrodactyly (1); esophageal squamous cell carcinoma (1); infection (1); lung adenocarcinoma (1); lymphoma (1); neurological disorders (1); oculodentodigital dysplasia (1); oral squamous cell carcinoma (1); preeclampsia (1); split-hand/split-foot malformation 4 (1); ZIKV infections (1).